SP1 (Sp1 transcription factor)
Diseases named in the same sentence as SP1 in open-access papers (continued):
Sharing a sentence is not in itself a finding about the gene and the disease.
lung cancer (continued). "From the study about the mechanical regulation of signaling pathway in lung cancer, some scholars find that inactivation of Akt signaling can inhibit the growth of human lung cancer cells through reducing SP1 and p65 protein expression." (PMID 27456341, 2016). "Previous studies have reported differences in the prognostic value of Sp1 overexpression in breast and lung cancer patients and also differences in the pro- and anti-carcinogenic role of Sp1 in MDA-MB-231 breast and A549 lung cancer cell lines." (PMID 26967243, 2016). "The results from Q-PCR indicated decreased mRNA expression of miR-29c and enhanced expression of Sp1 in lung cancer tissues." (PMID 27829234, 2016). "Some researcher discovered that upregulation of MALAT1 was mediated by the transcription factor Sp1 in A549 lung cancer cells." (PMID 27777857, 2016). "Nevertheless, the mechanism of Sp1 in the regulation of TGF-β-induced EMT in lung cancer needs to be further investigated." (PMID 27829234, 2016). "microRNA-29c (miR-29c) is identified to inhibit EMT, but the correlation between miR-29c and Sp1 in human lung cancer remain incompletely clarified." (PMID 27829234, 2016). "Sp1 had been found to be directly inhibited by miR-29c in lung cancer, and then we next investigated its role in tumor metastasis." (PMID 27829234, 2016). "For example, in comparison to normal tissues or cells Sp1 levels are higher in breast, thyroid, hepatocellular, pancreatic, colorectal, gastric and lung cancer." (PMID 25816367, 2015). "Collectively, our results show that solamargine inhibits the growth of lung cancer cells through inactivation of Akt, followed by reduction of SP1 and p65." (PMID 26689593, 2015). "Our results show that solamargine inhibits the growth of human lung cancer cells through inactivation of Akt signaling, followed by reduction of SP1 and p65 protein expression." (PMID 26689593, 2015). "CBP also has been reported to be cooperated with SP-1 and AP-2 to co-regulate hTERT expression in lung cancers." (PMID 26318425, 2015). "The CBP complexed with Sp1 or AP-2β was detected and considerably increased in lung cancer cell lines compared with that in normal lung cells." (PMID 25294805, 2014). "The levels of FOXO3 and Sp1 in the lung cancer cell lines, A549, H1299, CL 1-0, and CL 1-5, were studied." (PMID 24519909, 2014). "Because Sp1 is highly expressed in lung cancer, we studied the expression of Sp1 and miR-182 in various lung cancer cell lines and patient samples." (PMID 24519909, 2014). "We identified a novel Sp1-regulated miRNA, miR-182, in lung cancer cells and demonstrated that Sp1 downregulated FOXO3 expression by upregulating miR-182 expression." (PMID 24519909, 2014). "Because Sp1 is upregulated in lung cancer and the expression of its target genes is altered, we next examined the expression of these miRNAs in lung cancer." (PMID 24519909, 2014). "Previous study has also shown that hTERT expression is dependently regulated by activating specificity protein 1 (Sp1) in human lung cancer cells." (PMID 25294805, 2014). "Our previous study indicated that Sp1 is down regulated in the late stages of lung cancer progression." (PMID 24519909, 2014). "Recently, it has been also shown that TAp73 isoforms are overexpressed in response to overexpression of Sp1 transcription factor, which directly activates P1 promoter in lung cancer." (PMID 25071010, 2014). "In conclusion, we showed that miR-182 is an Sp1-activated miRNA, whose expression increased in lung cancer." (PMID 24519909, 2014). "In conclusion, in the early stages of lung cancer progression, Sp1 stimulates miR-182 expression, which in turn decreases FOXO3 expression." (PMID 24519909, 2014).
lung cancer (continued). "Nuclear extracts from normal lung HLF cells, immotolized HBE cells and lung cancer cells (H1299, A549) were prepared and incubated with a Sp1 or AP-2β antibody." (PMID 25294805, 2014). "The comparatively higher level of the acetylated Sp1 protein was detected in lung cancer cell lines (A549 and H1299) than that in normal lung cell lines (HLF)." (PMID 25294805, 2014). "In our previous studies of lung cancer, we found that Sp1 was highly upregulated in the early stages of cancer progression, but partially down regulated in the late stages." (PMID 24519909, 2014). "Our recent studies showed that Sp1 increased the growth of lung cancer cells, but inhibits metastatic activity." (PMID 24519909, 2014). "Our recent study indicated that overexpression of Sp1 enhances the proliferation of lung cancer cells, while represses metastasis." (PMID 24519909, 2014). "CD147 regulates the invasion and metastasis of human lung cancer and correlates with HO-1 or Sp1 in NSCLC." (PMID 25268615, 2014). "We also revealed that CBP interacts with and acetylates Sp1, thereby transactivating hTERT promoter and initiating hTERT expression, which is involved in lung cancer development." (PMID 25294805, 2014). "Our recent data suggested that Sp1 strongly affects upregulation of survivin in lung cancer cells at the transcriptional level." (PMID 23732337, 2013). "In lung cancer, we recently found that Sp1 accumulates in the early stage and then declines in the late stage, which is important for lung cancer cell proliferation and metastasis." (PMID 23148884, 2012). "The cytosolic phospholipases A2 (cPLA2) expression is regulated by Sp1 and c-Jun in lung cancer cells." (PMID 23148884, 2012). "The clinical implication of these results is that Sp1 inhibition is seemingly inappropriate for all patients with lung cancer ranging from stage I to IV." (PMID 23148884, 2012). "It has been shown to inhibit Sp1 and induce autophagy and apoptosis in lung cancer cells." (PMID 38764025, 2024). "Additionally, one previous report noted the use of miR-320a-3p delivery via gold nanoparticles as a means of targeting Sp1 in lung cancer." (PMID 37298699, 2023). "As a result of inhibiting SP1 for the upregulation of GZMB, lung cancer radiosensitivity may be elevated by AuNPs-si-SP1." (PMID 37510275, 2023). "Our previous study also found that Sp1 could directly mediate the transcription of PDSS2 in lung cancer cells." (PMID 36860919, 2023). "Although Sp1-low older female lung cancer patients also had a slightly poor prognosis, we speculate that this might be due to menopausal age." (PMID 35034634, 2022). "The role of interaction between Sp1 and ER in lung cancer progression is still unknown and will be clarified in this study." (PMID 35034634, 2022). "Previous studies have also indicated that Sp1 can coregulate its target genes together with the ER; therefore, in females with late-stage lung cancer, Sp1 may collaborate with the ER to regulate gene expression and thereby affect the survival rate." (PMID 35034634, 2022). "Taken together, these data indicate that estrogen may positively regulate lung cancer progression and that Sp1 downregulation may be involved in this effect." (PMID 35034634, 2022). "Premenopausal women with lung cancer and decreased Sp1 levels have a poor prognosis." (PMID 35034634, 2022). "The Sp1 level was significantly decreased in E2-A549 lung cancer cells." (PMID 35034634, 2022). "FKBP3 which is a member of FK506-binding proteins, could promote proliferation of lung cancer cells through regulating Sp1/HDAC2/p27, we assumed that its immunoregulation effects could be related to HDAC2." (PMID 33648465, 2021). "In lung cancer tissues, the positive rate of SP1 was found to be higher than that of APF." (PMID 34257529, 2021). "Moreover, inhibition of COX-2 caused attenuated migration and invasion of radiation-resistant lung cancer cells through the involvement of specificity protein 1 (Sp1)." (PMID 32171274, 2020).
lung cancer (continued). "In lung cancer, SP1 expression is correlated with the tumor progression." (PMID 32726929, 2020). "Moreover, metastasis associated lung adenocarcinoma transcript 1 (Malat1) regulates SP1 downstream protein expression in lung cancer by enhancing the stability and transcriptional activity of SP1." (PMID 30744670, 2019). "However, of the 66 patients with stage III and IV lung cancer, 30 (45.5%) exhibited high Sp1 expression, whereas 36 (54.5%) showed low Sp1 expression." (PMID 28831131, 2017). "Next, we found that Nm23-H1 can interact with hnRNPA2/B1, implying that these proteins might regulate Sp1 expression during lung cancer progression." (PMID 28831131, 2017). "Sp1-mediated microRNA-182 expression regulates lung cancer progression." (PMID 28422727, 2017). "Importantly, our study indicated a positive correlation between Sp1 and hnRNPA2/B1 expression during the late stages of lung cancer." (PMID 28831131, 2017). "Knockdown of Nm23-H1 inhibits lung cancer growth but increases lung cancer cell malignancy, which could be rescued by overexpression of Sp1, indicating that Nm23-H1-induced Sp1 expression is critical for lung cancer progression." (PMID 28831131, 2017). "Therefore, understanding the molecular mechanism(s) of how Sp1 is regulated is important for lung cancer prevention." (PMID 28831131, 2017). "In the present study, we found that the Nm23-H1/hnRNPA2/B1/Sp1 axis might be important for controlling lung cancer progression." (PMID 28831131, 2017). "We here found that, in lung cancer, Sp1 could form an auto-regulatory loop with TGF-β1, which enhanced TGFB1 transcription and TGF-β-induced EMT." (PMID 27829234, 2016). "Here, we confirmed decreased expression of miR-29c and enhanced expression of Sp1 in lung cancer tissues (n = 20) and found that Sp1 could be targeted and inhibited by miR-29c." (PMID 27829234, 2016). "We next verified the relationship between miR-29c and Sp1 in lung cancer." (PMID 27829234, 2016). "Our study provides the evidence that, in lung cancer, Sp1 could be repressed by miR-29c in translational level." (PMID 27829234, 2016). "In addition, previous studies also indicated that BA decreases Sp1 levels in prostate and lung cancers." (PMID 25909174, 2015). "Thus, we reasoned that regulation of SP1 played a crucial role in mediating solamargine-inhibited EP4 expression in lung cancer cells." (PMID 26689593, 2015). "Its ten hub genes were extracted and confirmed in the literature; seven of them (UBC, SRC, SP1, MYC, STAT3, RB1, and MAPK1) were verified to be associated with lung cancer, while the remaining three genes, JUN, NR3C1, and GRB2, were potentially new candidate lung adenocarcinoma-related genes." (PMID 26402252, 2015). "In addition, Sp1 levels strongly increase in the early stages and then decline in the late stages of lung cancer, indicating its dual function as both a metastasis suppressor and oncogene." (PMID 25839165, 2015). "Furthermore, we found a causative role of transcription factor SP1 that involved in the effects of solamargine on suppression of EP4 expression and lung cancer cell proliferation." (PMID 26689593, 2015). "The transcription factor Sp1 also regulates CD147 expression in human lung cancer." (PMID 25268615, 2014). "To determine whether CBP mediated the acetylation of the transactivators bound on hTERT promoter, we tested the effect of CBP on the acetylation level of the transactivator Sp1 in H1299 lung cancer cells." (PMID 25294805, 2014). "The results indicate that CBP mediates the tumor-specific acetylation of Sp1 in lung cancer cells." (PMID 25294805, 2014). "Suppression of Sp1 levels reduces tumor growth in mice implanted with lung cancer cells." (PMID 25418289, 2014).
lung cancer (continued). "On the other hand, the SP1 level was highly upregulated in patients with early stage and minimally invasive lung cancer cells and in patients with stage I lung cancer compared to that in lung cancers with high invasiveness and in patients with stage IV lung cancer." (PMID 25060396, 2014). "Sp1 is directly involved in nicotine-induced lung cancer cell growth." (PMID 25418289, 2014). "Because Sp1 accumulates in several types of cancer including lung cancer, understanding the Sp1 transcriptional regulatory network may provide novel insights into the molecular origins and treatment of lung cancer." (PMID 24519909, 2014). "Our recent study also indicates that BA could induce the sumoylation of Sp1 and then recruit the E3 ubiquitin ligase, RNF4, which contains SUMO-interacting motifs, to increase Sp1 ubiquitination, leading to Sp1 degradation in lung cancer." (PMID 23148884, 2012). "Analysis of damage patterns at CCCTC-binding factor and SP1 transcription factor binding sites indicates that BPDE damage formation is also suppressed by these DNA-bound proteins, and this damage modulation correlates with mutation patterns at these binding sites in lung cancers." (PMID 41707998, 2026). "Moreover, it was shown that Sp1 promoted proliferation and inhibit apoptosis in lung cancer cells." (PMID 37147632, 2023). "However, what is the effect of E2 on Sp1 levels in lung cancer cells?" (PMID 35034634, 2022). "However, in late-stage lung cancer, a low level of Sp1 is correlated with a poor prognosis, but the detailed mechanism remains unknown." (PMID 35034634, 2022). "Interestingly, we found that E2 treatment could decrease Sp1 levels in lung cancer cells through a decrease in Sp1 protein stability." (PMID 35034634, 2022). "However, regulation of Nm23-H1 and Sp1 in lung cancer progression including proliferation and malignancy, remains unclear." (PMID 28831131, 2017). "Overexpression of Sp1 in Nm23-H1-silenced cells partially abolish the effect of Nm23-H1 on cancer migration, implying that other pathway(s) might also be regulated by Nm23-H1 to affect lung cancer progression." (PMID 28831131, 2017). "In this study, we investigated the potential mechanism of lung cancer metastasis and found that Sp1 could be inhibited by miR-29c in lung cancer and inhibition of miR-29c/ Sp1 dramatically enhanced the cell migration and invasion via the regulation of TGF-β-induced EMT." (PMID 27829234, 2016). "95C cell and A549 cells were ectopically expressed of miR-29c mimics and Sp1 could remarkably enhance the ability of migration and invasion which indicated that the overexpression of Sp1 could abrogate the miR-29c-induced inhibition of metastasis in lung cancer." (PMID 27829234, 2016). "Moreover, the level of Sp1 was increased upon the treatment of TGF-β1 in two lung cancer cells, suggesting that miR-29c might function as a tumor suppressor and impair the TGF-β1-induced EMT." (PMID 27829234, 2016). "Whether Sp1 or miR-182 regulates TIMP-1 in lung cancer needs to be addressed in future studies." (PMID 24519909, 2014). "Furthermore, CBP was found to interact with and acetylate transactivator Sp1 in lung cancer cells." (PMID 25294805, 2014). "Knockdown of SP1 decreased basal expression of ZFAS1, and significantly attenuated CSC-mediated upregulation of this lncRNA in NREC and lung cancer cells." (PMID 40211119, 2025). "Our findings suggest that five genes (SETDB1, TWIST1, HDAC1, SP1, and GRIA2) are likely involved in the dystropic relationship observed between Huntington’s disease and non–small cell lung cancer." (PMID 40843670, 2025). "Major TFs SP1 and CTCF were also identified, highlighting complex transcriptional and post-transcriptional regulation in COPD–lung cancer progression." (PMID 40826767, 2025). "Drug resistance and stemness in GBM were also associated with Sp1 in another study and in glioma, HDAC/Sp1 regulation of BMI1 enhanced stemness; this exhibited some overlap with lung cancer cells and BMI1." (PMID 36982239, 2023).
lung cancer (continued). "Investigation of the molecular mechanism showed that E2 increases RNF4 expression to reduce Sp1 levels, thereby enhancing CD44 expression through downregulation of several miRNAs, and this leads to a poor prognosis in young women with lung cancer." (PMID 35034634, 2022). "Our study also indicated that E2 reduced Sp1 levels to inhibit miRNA expression, in turn enhancing CD44 expression, subsequently resulting in a poor prognosis in women with lung cancer." (PMID 35034634, 2022). "Samples obtained from lung cancer patients were used to study the mRNA level of CD44 by q-PCR and the protein levels of Sp1 and CD44 by immunoblot and immunohistochemistry." (PMID 35034634, 2022). "Sp1 inhibited CD44 expression by increasing the expression of miR-3194-5p, miR-218-5p, miR-193-5p, miR-182-5p and miR-135-5p, ultimately resulting in lung cancer malignancy." (PMID 35034634, 2022). "Overexpression of GFP-Sp1 decreased the CD44 level, and Sp1 knockdown increased the CD44 level in A549 and H1299 lung cancer cell lines, indicating that Sp1 negatively regulates CD44 expression in lung cancer cells." (PMID 35034634, 2022). "It has been found that AuNPs can also act as a carrier for the delivery of siRNA and miRNA to down-regulate the expression of PD-L1 and Sp1, respectively, in lung cancer and can also provide additional PTT effects against lung cancer." (PMID 35778747, 2022). "The mRNA levels of Sp1 and CD44, including CD44s and CD44st, exhibited inverse correlations in the clinical lung cancer cohorts." (PMID 35034634, 2022). "They reported that SMARCA4 interacted with Sp1 to activate LTBP2 transcription, thus promoting lung cancer progression." (PMID 33853662, 2021). "For instance, in lung cancer, it inhibits the expression of EMT induced by SP1/TGF-0205 through inhibiting the expression of SP1/TGF-0205 in vivo, thereby exerting a tumor suppressor effect." (PMID 32461938, 2020). "We previously demonstrated that SM inhibited the growth of human lung cancer cells through inactivation of phosphatidylinositol 3‐kinase (PI3‐K)/Akt signaling pathway and reduction of transcription factor SP1 and p65 proteins." (PMID 31823440, 2020). "During lung cancer formation, nucleolin was recruited to the 5′-UTR of Sp1 mRNA to enhance cap-independent translational activity in the cytoplasm." (PMID 32851058, 2020). "Recent research provided evidence that SP1 participated in the activity of Oct4 suppressing PTEN, leading to the activation of AKT signaling and drug resistance in lung cancer." (PMID 31543507, 2019). "Overexpression of Sp1 significantly inhibited PDSS2 promoter activity, as well as its endogenous expression, at both mRNA and protein levels in lung cancer cells." (PMID 31783675, 2019). "Functional analysis revealed that the Sp1 transcription factor is a critical regulator for the constitutive expression, as well as its repressed expression, of PDSS2 in lung cancer cells." (PMID 31783675, 2019). "Sumoylation of Sp1 at Lys16 increases the recruitment of RNF4, the Sp1 E3-ligase, resulting in the induction of Sp1 degradation at the late stages of lung cancer progression." (PMID 28831131, 2017). "In conclusion, Nm23-H1 and hnRNPA2/B1 regulates Sp1 expression together to affect cell growth and the EMT during lung cancer progression." (PMID 28831131, 2017). "Finally, Nm23-H1 and hnRNPA2/B1 were present at high levels in nearly all of the examined patients with early-stage lung cancer, indicating that during early-stage lung cancer, the Nm23-H1/hnRNPA2/B1/Sp1 regulatory pathway might promote cancer tumorigenesis by enhancing Sp1 expression." (PMID 28831131, 2017). "In this study, we used LC/MS/MS to identify the proteins that were bound to the Sp1 IRES-motif, and clarified their effect on Sp1 expression during lung cancer progression." (PMID 28831131, 2017).